CD93 (CD93 molecule)
Diseases named in the same sentence as CD93 in open-access papers (continued):
Sharing a sentence is not in itself a finding about the gene and the disease.
tumor (continued). "Subsequent studies have shown that CD93 is a downstream effector of VEGF, a potent tumor-derived angiogenesis stimulator, and its expression is significantly downregulated when VEGF is inhibited." (PMID 40943530, 2025). "In mouse models, blocking the CD93 pathway significantly improves CAR-T cell therapy efficacy and synergizes with adoptive cell therapy (ACT) to promote tumor vascular maturation." (PMID 40943530, 2025). "In subsequent studies, CD93 has been shown to be a downstream effector of VEGF, a potent stimulator for tumor-derived angiogenesis, and its expression significantly downregulated upon VEGF inhibition." (PMID 38468017, 2024). "CD93 is a receptor for insulin-like growth factor binding protein 7 (IGFBP7, also known as angiomodulin), which is secreted by tumor vessels and contributes to vascular abnormalities." (PMID 38441970, 2024). "CD93 colocalized with the endothelial marker CD31, indicating a predominant expression in tumor endothelial cells." (PMID 38441970, 2024). "CD93 appears to be a promising therapeutic target for HCC due to its significant role in promoting pathological angiogenesis, tumor progression, and immune cell infiltration, although there are currently no ongoing clinical trials for HCC." (PMID 38999940, 2024). "Blockade of the CD93/IGFBP7 interaction by monoclonal antibodies thus promoted vascular maturation and reduced leakage, leading to reduced tumor hypoxia and increased tumor perfusion." (PMID 39045455, 2024). "Tumor vessel parameters, including CD31-positive area, vascular volume, length, and diameter were similar in tumors grown in wild-type and CD93–/– mice." (PMID 38441970, 2024). "Given the structural similarity between group XIV CTLDs and selectins, and the documented cell–cell adhesion properties of CD93, it is plausible that group XIV proteins can likewise directly facilitate circulating tumor cell adhesion and intravasation." (PMID 38468017, 2024). "Following recruitment, Notch-activated macrophages suppress the proliferation of tumor-infiltrating T cells and their tumor-killing activity by enhancing CD14 and CD93 secretion." (PMID 39766289, 2024). "Anti-CD93 and anti-VEGFR suppress subcutaneous tumor growth by normalizing tumor vasculature, thereby having similar antitumor effects." (PMID 38250037, 2024). "Subsequently, we found that miR-5110 levels in EVs from tumor tissues (TT-EVs) of LLC lung tumor-bearing mice and serum EVs (sEVs) were both inversely correlated with Cd93 mRNA level in pMCs of these mice." (PMID 38250037, 2024). "To investigate the mRNA expression of CD93 in tumor and normal tissues, we utilized an online tool, Tumor Immune Estimation Resource (TIMER), to find that the expression of CD93 between various tumors and adjacent tissues was tremendously different." (PMID 37483608, 2023). "Third, the expression levels of CD93, IGFBP7, and MMRN2 in various solid tumors and their relationship with the clinical characteristics of tumor patients should be further investigated." (PMID 37660019, 2023). "Moreover, anti-CD93 antibodies may be useful in cancer treatment since they can improve immunotherapy by increasing vascular permeability and immune cell infiltration in tumor tissue." (PMID 37443812, 2023). "CD93 is of great importance in EC adhesion and migration that the CD93-MMRN2 complex mediates tumor angiogenesis by forming a fibrillar fibronectin network." (PMID 35978433, 2022). "CD93-mediated neovascularization and the remodeling of blood brain barrier (BBB) provided ideal nutritional support for tumor cells, which formed an invasive niche suitable for the progression of HGG." (PMID 36006582, 2022). "Furthermore, CD93 could promote β1 integrin activation and fibronectin fibrillogenesis, thus performing a significant role in vascular maturation and formation of the extracellular matrix during tumor angiogenesis." (PMID 35265666, 2021).
tumor (continued). "This tumor angiogenesis core gene signature also included CLEC14A and CD93, which together with endosialin and thrombomodulin constitute a C-type lectin family that are frequently up-regulated in tumor vessels." (PMID 31690961, 2020). "Finally, as CLEC14A and CD93 have been described as proteins highly expressed in the tumour vasculature, with roles in angiogenesis, it remains to be investigated whether these molecules are also expressed and have roles in other routes in which a tumour can acquire a blood supply." (PMID 31287944, 2019). "Taken together, our data support a key role of CD93 and MMRN2 in fibronectin fibrillogenesis, which is crucial for tumor angiogenesis and vascular integrity." (PMID 29763414, 2018). "CD93 is essential for β1 integrin activation and fibronectin fibrillogenesis in GL261 tumor vessels." (PMID 29763414, 2018). "While CD93 and CLEC14A are expressed in tumor endothelial cells, endosialin is mainly expressed in pericytes." (PMID 29763414, 2018). "This research suggests that inhibiting CD93 primarily improves vascular function, and targeting the IGFBP7/CD93 pathway could be a safe, durable strategy to enhance tumor vasculature." (PMID 40943530, 2025). "The use of a CD93 monoclonal antibody was shown to promote vascular maturation, alleviate tumor hypoxia, and increase tumor perfusion without significantly affecting vascular homeostasis in healthy organs, unlike anti-VEGFR monoclonal antibodies." (PMID 40943530, 2025). "MP2 lysate-pulsed 1st and 2nd Gen DCs significantly reduced tumor burden compared to untreated or UTD DC-treated mice, highlighting the capacity of antigen-loaded DCs engineered to overexpress CD93, CD40L, and CXCL13 to drive robust anti-tumor immunity in the Hu-BLT model." (PMID 41295503, 2025). "We also confirm that the modifications made to the LVV have not compromised the tumor-killing efficacy of engineered cells overexpressing CD93, CD40L, and CXCL13." (PMID 41295503, 2025). "Nonetheless, normalization of tumor vasculature has been found to promote a host of favorable alterations to the TME, as we have recently demonstrated in preclinical murine models by disrupting CD93 interaction with IGFBP7/MMRN2." (PMID 38468017, 2024). "Blockade of CD93 with monoclonal antibodies against CD93 (anti-CD93) markedly inhibited lung tumor growth by inducing CCL21 secretion from pMCs and preventing tumor angiogenesis, thus showing better efficacy than blocking vascular endothelial growth factor receptor (VEGFR)." (PMID 38250037, 2024). "Cluster of Differentiation 93 (CD93) plays an important role in angiogenesis and is considered an important target for inhibiting tumor angiogenesis, but there are currently no therapeutic antibodies against CD93 in the clinic." (PMID 38751868, 2024). "Interestingly, we also anlysized peritoneal metastases from GCPM patients and found that CD93, COL3A1, COL4A1 expression were higher in metastases than in the primary tumor." (PMID 36690975, 2023). "Our analysis indicated a negative relationship between CD93 expression and tumor purity in STAD (Spearman rho = -0.191, p = 1.76e-04)." (PMID 36761750, 2023). "In summary, lnc-RFNG-1, lnc-TRIM28-14, CD93, COL3A1 and COL4A1 could be novel tumor biomarkers and potential therapeutic targets for GCPM." (PMID 36690975, 2023). "Among them, CD93 and HIST1H2BC were specifically expressed in neutrophils and constituted the distinctive transcriptional profile of neutrophils, facilitating the identification of neutrophils within the tumor microenvironment." (PMID 36339597, 2022). "Furthermore, the pathway activated by the interaction between CD93 and insulin-like growth factor binding protein 7 (IGFBP7), an ECM protein upregulated in tumor blood vessels, contributes to abnormal tumor vasculature." (PMID 34830297, 2021).
tumor (continued). "As adhesion molecule, CD93 contributes to EC adhesion and migration through its interaction with Multimerin-2 (MMRN2), an endothelial-specific member of the EDEN family, consistently deposited in the extracellular environment of tumor vasculature." (PMID 31138217, 2019). "Our data demonstrate a nonredundant role of CD93 in orchestrating integrin activation and fibronectin organization during tumor angiogenesis." (PMID 29763414, 2018). "CD93 is a member of group XIV in the C-type lectin superfamily, which also includes thrombomodulin, CLEC14A, and endosialin, all of which are highly expressed in tumor vessels." (PMID 29763414, 2018). "In normal vessels adjacent to the tumor site, β1 integrin activation was low or absent in both WT and CD93–/– mice." (PMID 29763414, 2018). "No obvious differences in fibronectin deposition were found in the normal vasculature of CD93–/– mice compared with WT mice, and fibronectin levels in normal vessels were considerably lower than those in tumor vessels." (PMID 29763414, 2018). "CD93 and MMRN2 interact in human endothelial cells and colocalize in tumor vessels." (PMID 29763414, 2018). "To determine whether the observed interaction between CD93 and MMRN2 is likely to occur in tumor vessels, we examined the expression pattern of MMRN2 in tumors." (PMID 29763414, 2018). "A similar result was obtained when a macrophage signature comprising a subset of eight widely used markers (CD14, CD105, CD11b, CD68, CD93, CD33, IL-4R and CD163) for the mononuclear phagocyte system was used to identify tumours highly infiltrated by macrophages." (PMID 29921315, 2018). "Analysis of HCmel12 tumors injected subcutaneously in CD93–/iECKO mice showed a trend toward decreased tumor growth compared with the control group; however, statistical significance was not reached, likely due to variation in CD93 expression in CD93–/iECKO mice." (PMID 38441970, 2024). "The pleural Cd93 but not Ccl21a mRNA level was also upregulated in tumor-bearing mice." (PMID 38250037, 2024). "Recent work detailing blockade with a CD93 mAb has led to interesting and promising results toward tumor vessel normalization rather than depletion as seen in antibody-directed binding to other group XIV CTLDs such as CD248 and CLEC14a as will be discussed in subsequent sections." (PMID 38468017, 2024). "Consequently, we hypothesized that lnc-TRIM28-14, CD93 and COL4A1 could regulate GCPM and could be novel tumor markers and potential therapeutic targets for GCPM." (PMID 36690975, 2023). "We further found that expression of CD93 was correlated with tumor size, differentiation and peritoneal metastasis; that of COL3A1 was correlated with differentiation, depth of invasion, peritoneal metastasis and TNM stage; that of COL4A1 was correlated with tumor size and peritoneal metastasis." (PMID 36690975, 2023). "While thrombomodulin, CD93 and CLEC14A are mainly expressed by endothelial cells, CD248 is expressed by vasculature-associated pericytes, activated stromal fibroblasts, mesenchymal stem cells and tumor cells, but not in the endothelium." (PMID 37443812, 2023). "Therefore, we employed the most up-to-date data from numerous databases, including TCGA, Cancer Cell Line Encyclopedia (CCLE), Genotype Tissue-Expression (GTEx), cBioPortal, and tumor immune single-cell hub (TISCH), to systematically evaluate the correlation of CD93 with 33 types of cancer." (PMID 35242761, 2022). "Notably, there were obvious differences in CD93 expression between some tumor tissues and corresponding adjacent noncancerous tissues." (PMID 35242761, 2022). "In addition, CD93 was highly expressed in vascular endothelial cells of tumor tissues, but weakly expressed in non-proliferative vascular endothelial cells." (PMID 35265666, 2021).
tumor (continued). "This superior anti-metastatic activity is likely attributable to the combinatorial expression of CD40L, CD93, and CXCL13 and the promoter optimization of the LVV, which may enhance antigen presentation, T cell recruitment, and improved immune modulation in the tumor microenvironment." (PMID 41295503, 2025). "Further, upregulation of selectins and CD93, CD248, and CLEC14a on tumor ECs prompt investigation as to whether group XIV CTLDs can serve as a mediator or master regulator of the activated EC phenotype in the face of tumor-derived signals as is described for E-selectin." (PMID 38468017, 2024). "Moreover, blocking CD93 with specific agents (e.g., monoclonal antibodies, non-coding RNA, etc.)can favor immunotherapy by increasing vascular permeability and immune cell infiltration in tumor tissue." (PMID 37443812, 2023). "However, our analysis indicated a negative contact between CD93 and tumor purity in most cancers." (PMID 35242761, 2022). "Unlike CD93 and CLEC14a but like CD248, expression of TM on tumor cells themselves seems to carry more relevancy to cancer biology than angiogenesis." (PMID 38468017, 2024). "In the prospective cohort, two proteins; CD93 and CD84, displayed higher levels within the tumor samples when compared to non-tumors." (PMID 34885093, 2021).
cancer (31 papers, 2014 to 2025). A tumor composed of atypical neoplastic, often pleomorphic cells that invade other tissues. "Then, the associations of CD93 expression with multiple checkpoint markers were compared across different cancer types." (PMID 35242761, 2022). "To explore the correlation between CD93 expression and immune infiltration in human pan-cancer, we mainly focused on the association between CD93 and infiltrating immune cells by the TIMER2.0 database in various cancers." (PMID 35242761, 2022). "All of these data implied that the expression of CD93 was significantly associated with patient prognosis in multiple cancer types, especially in patients with KIRP, LGG, UVM, and KIRC." (PMID 35242761, 2022). "Similar to immunosuppressive factors, CD93 expression was positively associated with immunostimulatory genes in all cancers we analyzed but TGCT." (PMID 35242761, 2022). "We also demonstrated that CD93 can be a potential diagnostic biomarker in serval types of cancer via ROC curves." (PMID 35242761, 2022). "The correlation of CD93 levels with mutational status of other gene in these cancers was also analyzed." (PMID 36389798, 2022). "Meanwhile, survival analysis based on pan-cancer showed that CD93 was a risk factor in most tumors and that an increased expression of CD93 usually indicated poor prognosis." (PMID 35265666, 2021). "IGFBP7/CD93 overexpression was associated with poor treatment response in cancer patients treated with anti-PD1/PDL1." (PMID 35265666, 2021). "Additionally, pan-cancer survival analysis reveals that elevated CD93 expression generally poses a risk in most tumors, correlating with advanced TNM stages." (PMID 40943530, 2025). "Additionally, high CD93 expression is primarily linked to inflammation and angiogenesis, underscoring its critical role in cancer, inflammatory diseases, and homeostasis." (PMID 40943530, 2025). "The authors found that silencing CD93 in endothelial cells caused an increase in dystroglycan expression, a laminin-binding protein involved in angiogenesis and overexpressed in vascular endothelial cells within malignant tumors." (PMID 37443812, 2023). "The finding that high expression of CD93 was mainly associated with inflammation and angiogenesis may imply that not only does CD93 exerts a crucial role in cancer, but it may be also important in inflammatory diseases and general homeostasis." (PMID 35242761, 2022). "We next explored the association between CD93 expression and immune-related genes, which includes HLA, immunostimulatory genes, immunosuppressive genes, chemokines, and chemokine receptor proteins, in 33 types of cancer." (PMID 35242761, 2022). "Now that CD93 is known to be differentially expressed in certain cancers, we explored whether its expression is associated with the prognosis of different cancers." (PMID 35242761, 2022). "CD93 mRNA expression associated with patient prognosis in many cancers." (PMID 36389798, 2022). "Among these cancers, CD93 was associated with six infiltrating immune cells of all cancers." (PMID 35242761, 2022). "The exact mechanism of the T/T genotype is currently not known, but it is associated with increased tissue level of CD93 in the cancer that might affect angiogenesis, growth and spreading." (PMID 26008729, 2015). "DCBY 02, Anti CD93 antibody (China Resources Biopharmaceutical), JS013, and DCSZ11 are all CD93 monoclonal antibodies aimed at treating cancer by inhibiting CD93." (PMID 40943530, 2025). "Single-cell sequencing analysis indicates that macrophages, astrocytes, cancer-associated fibroblasts (CAFs), T cells, B cells, ECs, neutrophils, and cancer cells are the primary CD93-expressing cells within the TME." (PMID 40943530, 2025). "Between 2021 and 2022, Tong, Guo, and their team examined CD93 expression across various cancers using multiple public databases." (PMID 40943530, 2025).